TRPV6 (transient receptor potential cation channel subfamily V member 6)
Diseases named in the same sentence as TRPV6 in open-access papers (continued):
Sharing a sentence is not in itself a finding about the gene and the disease.
esophageal squamous cell carcinoma (2 papers, 2016 to 2020). Esophageal squamous cell carcinoma (ESCC) is a type of esophageal carcinoma (EC) that can affect any part of the esophagus, but is usually located in the upper or middle third. "The association between the expression of TRPV6 and clinical outcome in esophageal squamous cell carcinoma (ESCC) has not been studied yet." (PMID 26818094, 2016).
gastric cancer (2 papers, 2019 to 2020). A primary or metastatic malignant neoplasm involving the stomach. "In gastric cancer, the increase in free Ca2+ in mitochondria via stimulation of TRPV6 protein was shown to result in cancer cell apoptosis." (PMID 31683902, 2019).
Gitelman syndrome (2 papers, 2021 to 2025). Gitelman syndrome (GS), also referred to as familial hypokalemia-hypomagnesemia, is characterized by hypokalemic metabolic alkalosis in combination with significant hypomagnesemia and low urinary calcium excretion. "One of the most significantly up-regulated transcripts was Trpv6 (8.89-fold increase), which has been reported to increase in Gitelman syndrome." (PMID 34028587, 2021). "Studies in knock-in mouse models of Gitelman syndrome (with SLC12A3 mutations) suggest that increased expression of TRPV5 and TRPV6 channels in the DCT may also contribute." (PMID 40777730, 2025).
hepatocellular carcinoma (2 papers, 2022 to 2023). A malignant tumor that arises from hepatocytes. "Despite the incomplete elucidation of the TRPV6 mechanism that hinders apoptosis of hepatoma cells, it presents fresh perspectives for investigators." (PMID 37569884, 2023). "Moreover, previous studies have reported the downregulation of the TRPV6 gene in esophageal, non-small cell lung, and hepatocellular carcinoma, as well as in renal cancer." (PMID 36012311, 2022).
invasive ductal carcinoma (2 papers, 2023). "In a study of 59 women with invasive ductal carcinoma, TRPV6 expression was found to be elevated compared to both adjacent non-cancerous tissue and ductal carcinoma in situ (DCIS)." (PMID 37240443, 2023).
leukemia (2 papers, 2013 to 2024). A malignant (clonal) hematologic disorder, involving hematopoietic stem cells and characterized by the presence of primitive or atypical myeloid or lymphoid cells in the bone marrow and the blood. "TRPV5 and TRPV6 are highly expressed in malignant states of human lymphocytes and leukemia Jurkat T cells, where they regulate cell proliferation." (PMID 39027429, 2024). "TRPV6 mRNA is elevated in various tumor cell lines including those of colon, human leukemia and prostate." (PMID 23554944, 2013). "Other studies have shown that TRPV5 and TRPV6 are expressed in leukemia cell K562, and the increase in channels activates Ca2+/calmodulin-dependent kinase II (CaMKII), thereby increasing intracelluar Ca2+, regulating cell proliferation, differentiation, and resistance to apoptosis." (PMID 39027429, 2024).
lung carcinoma (2 papers, 2017 to 2020). "Moreover, capsaicin activates TRPV6 instead of TRPV1 to induce apoptosis in GC and lung cancer cells." (PMID 33008449, 2020).
melanoma (2 papers, 2013 to 2017). A malignant, usually aggressive tumor composed of atypical, neoplastic melanocytes. "3.3, TRPM8, TRPV6, SERCA2, SERCA3, PMCA4; bladder: TRPV1; melanoma:TRPM1; oral: PMCA1, SERCA2; thyroid: TRPV6, SERCA2; gastric: IP3R3, Cav." (PMID 28486397, 2017).
metastatic disease (2 papers, 2020 to 2023). "TRPV6 expression was also associated with metastatic disease." (PMID 37240443, 2023).
neonatal hyperparathyroidism (2 papers, 2021 to 2023). "Transient severe neonatal hyperparathyroidism has been reported in patients with missense variants of TRPV6, inherited in an autosomal recessive manner." (PMID 37810884, 2023).
osteoarthritis (2 papers, 2023 to 2024). A noninflammatory degenerative joint disease occurring chiefly in older persons, characterized by degeneration of the articular cartilage, hypertrophy of bone at the margins and changes in the synovial membrane. "Furthermore, TRPV6 knockout mice exhibited pronounced osteoarthritis changes, characterized by cartilage fibrillation, eburnation, and loss of proteoglycans." (PMID 38540712, 2024). "Additionally, they explored bone structure and observed osteoarthritis changes in the knee joints of TRPV6 gene knockout mice." (PMID 38540712, 2024).
pancreatic ductal adenocarcinoma (2 papers, 2023 to 2026). An infiltrating adenocarcinoma that arises from the epithelial cells of the pancreas. "In this study, we investigated the role of TRPV6 channels in pancreatic ductal adenocarcinoma (PDAC), a highly aggressive and lethal cancer type." (PMID 38136316, 2023).
renal cell carcinoma (2 papers, 2014 to 2016). "Although the study only included twenty seven patients with renal cell carcinoma and did not detect the expression of TRPV6 in renal cell lines, the findings lend support to our claim that TRPV6 could be down-regulated in some cancer types." (PMID 26818094, 2016).
small cell lung carcinoma (2 papers, 2016 to 2025). Small cell lung cancer (SCLC) is a highly aggressive malignant neoplasm, accounting for 10-15% of lung cancer cases, characterized byrapid growth, and early metastasis. "This TRPV6 inhibitor reduces cancer growth and spread that is mediated by Ca2+, for instance in small cell lung cancer (SCLC)." (PMID 40813985, 2025).
acute lymphoblastic leukemia (1 paper, 2022). Leukemia with an acute onset, characterized by the presence of lymphoblasts in the bone marrow and the peripheral blood. "TRPV1, TRPV6 and TRPM2 contribute to the growth of cells derived from acute lymphoblastic leukemia (ALL)." (PMID 36330491, 2022).
acute myocardial infarction (1 paper, 2024). Necrosis of the myocardium, as a result of interruption of the blood supply to the area. "In our clinical research, we have also found that patients with lower serum TRPV6 levels, such as those with acute myocardial infarction, have higher levels of CK-MB and NT-pro-BNP." (PMID 39742020, 2024).
acute pancreatitis (1 paper, 2022). An acute inflammatory process that leads to necrosis of the pancreatic parenchyma. "Our data also shows that TRPV6 mRNA is upregulated in mice during caerulein-induced, early-onset acute pancreatitis." (PMID 36699452, 2022). "Trpv6 was significantly upregulated in early stages of caerulein-induced acute pancreatitis." (PMID 36699452, 2022).
adenoma (1 paper, 2014). A neoplasm arising from the epithelium. "In this work, the presence of TRPV5 and TRPV6 proteins and of their mRNAs was studied by using human parathyroid tissues, while their cellular localization and time expression were evaluated by immunocytochemical assay on primary human adenoma parathyroid cells." (PMID 25164318, 2014).
asthma (1 paper, 2022). "In most of the cells, TRP channels are expressed, and strong evidence for an essential role in airway function and associated diseases, such as CF, asthma, fibrosis and edema was demonstrated for TRPA1, TRPC6, TRPM2, TRPM5, TRPM7, TRPV2, TRPV4 and TRPV6." (PMID 36139480, 2022).
atherosclerosis (1 paper, 2024). A disease characterized by the build-up of fatty material and calcium deposition in the arterial wall resulting in partial or complete occlusion of the arterial lumen. "We further investigated the role of TRPV6 in atherosclerosis by transfecting ox-LDL-treated cells with siRNAs (si-TRPV6#1 and si-TRPV6#2) and TRPV6 overexpression plasmids (oe-TRPV6#1 and oe-TRPV6#2)." (PMID 39742020, 2024). "We further demonstrated that TRPV6 inhibited inflammatory response and apoptosis in atherosclerosis through the regulation of PKA/UCP2." (PMID 39742020, 2024). "Our study highlights the pivotal role of TRPV6 in mitigating apoptosis and inflammatory responses in atherosclerosis cell models via modulation of the PKA/UCP2 signaling pathway." (PMID 39742020, 2024). "IFC experiments demonstrated that the expression of TRPV6 was decreased significantly in the atherosclerosis cell model." (PMID 39742020, 2024). "For the expression of TRPV6 in atherosclerosis mice, we performed oil red O staining on mouse aortic sinus tissue sections." (PMID 39742020, 2024). "Here, we demonstrated that the expression of TRPV6 was significantly decreased in both in vivo and in vitro models of atherosclerosis." (PMID 39742020, 2024). "Our findings suggest that TRPV6, through the regulation of the same downstream signaling pathway, PKA/UCP2, inhibited apoptosis and inflammatory response in the atherosclerosis cell model." (PMID 39742020, 2024). "This research is aimed at unravelling the intricate relationship between TRPV6, PKA, UCP2, and atherosclerosis." (PMID 39742020, 2024). "Further mechanistic studies have revealed that TRPV6 regulates the PKA/UCP2 signaling pathway, thus modulating inflammatory response and cell apoptosis in atherosclerosis." (PMID 39742020, 2024). "To further investigate the mechanism of action of TRPV6 and PKA in the atherosclerosis cell model, we employed CHIP and CoIP assays to explore the interaction and regulatory relationship between TRPV6 and PKA." (PMID 39742020, 2024).
autism (1 paper, 2021). Persistent deficits in social interaction and communication and interaction as well as a markedly restricted repertoire of activity and interest as well as repetitive patterns of behavior. "We also observed unique genes for specific subgroups such as TRPV6 for autism or ATXN1 for AS." (PMID 33719335, 2021).
basophilic leukemia (1 paper, 2017). "For instance, the transcripts of TRPV1, TRPV2, TRPV4, and TRPV6 were identified in RBL-2H3 cells (rat basophilic leukemia cell line), TRPV1, TRPV2, and TRPV6 in HMC-1, and TRPV2 in human lung, skin, and cord blood-derived mast cells." (PMID 28158279, 2017).
bone metabolism disorders (1 paper, 2021). "Bianco et al35 found that Trpv6–/– mice had bone metabolism disorders, which manifested as intestinal calcium absorption dysfunction and decreased bone density." (PMID 33159483, 2021).
brain tumours (1 paper, 2022). "Among these TRP family genes, it has been shown previously that TRPV2 in brain tumours, TRPV6 in PRAD, and TRPC6 in STAD promote tumour progression—which validates our analysis." (PMID 35493463, 2022).
breast adenocarcinoma (1 paper, 2024). "This suggests that TRPV6 may be a new target for the development of calcium channel inhibitors for the treatment of breast adenocarcinoma expressing TRPV6." (PMID 38534438, 2024).
Caffey disease (1 paper, 2018). Caffey disease is an osteosclerotic dysplasia characterized by acute inflammation with massive subperiosteal new bone formation usually involving the diaphyses of the long bones, as well as the ribs, mandible, scapulae, and clavicles. "Antenatal Caffey disease is very rare and although heterozygote COL1A1 mutations have been identified in some cases, genetic heterogeneity seems likely and TRPV6 may be a candidate worth investigation in unsolved cases." (PMID 30144375, 2018).
cervical adenocarcinoma (1 paper, 2022). An adenocarcinoma arising from the cervical epithelium. "TRPV6 was expressed in lower level in CSCC and higher in cervical adenocarcinoma compared to normal group." (PMID 36072430, 2022).
colon adenocarcinoma (1 paper, 2020). "We found that most of these mutants induced a strong gain of invasiveness of colon adenocarcinoma SW480 cells, both for TRPV4 and TRPV6." (PMID 32186440, 2020).
colorectal cancer (1 paper, 2014). A primary or metastatic malignant neoplasm that affects the colon or rectum. "In this study, we show for the first time that TNFα significantly reduced CYP27B1 mRNA expression and expression of the calcium ion channel TRPV6 in colorectal cancer cells." (PMID 24120915, 2014).
coronary artery disease (1 paper, 2024). "By shedding light on the role of the TRPV6/PKA/UCP2 pathway in inhibiting inflammatory response and cell apoptosis in coronary atherosclerotic plaques, this study provides valuable insights into potential therapeutic targets for treating coronary artery disease (CAD)." (PMID 39742020, 2024).
coronary atherosclerosis (1 paper, 2024). Atherosclerosis of the coronary vasculature. "TRPV6 is involved in various pathological processes that engage multiple signaling pathways, including CaM, CaMKII, CaMKK, PI3K/Akt/Gsk-3β, and MAPK/JNK, many of which are implicated in the pathophysiology of coronary atherosclerosis." (PMID 39742020, 2024). "However, to date, no research has investigated the role and mechanisms of TRPV6 in coronary atherosclerosis." (PMID 39742020, 2024).
glioma (1 paper, 2024). A benign or malignant brain and spinal cord tumor that arises from glial cells (astrocytes, oligodendrocytes, ependymal cells). "In oncology, synthetic peptides derived from venoms have reached the clinical development stage, including the chlorotoxin-derived peptide 131I-TM601 for the treatment of gliomas and the soricidin-derived peptide SOR-C13 for solid tumors overexpressing the TRPV6 ion channel." (PMID 38611925, 2024).
hearing loss (1 paper, 2025). "This highlights a gap in understanding: while TRPV5/TRPV6 are linked to calcium homeostasis and age-related hearing loss, their precise mechanistic roles (e.g., in sensory transduction vs. cellular calcium signaling) require further investigation." (PMID 40688696, 2025).
hereditary pancreatitis (1 paper, 2022). "In conclusion, we report a novel frameshift mutation in TRPV6 in an Indian family with hereditary pancreatitis that renders the mutant protein inactive." (PMID 36699452, 2022).
Hyperglycemia (1 paper, 2018). An increased concentration of glucose in the blood. "Surprisingly, hyperglycemia stimulation did not alter TRPV6 expression in rat kidneys." (PMID 30459613, 2018).
Hypomagnesemia (1 paper, 2019). An abnormally decreased magnesium concentration in the blood. "In mice, maternal hypomagnesemia did not change the activity of TRPM7 and TRPM6 ion channels but increased the expression of placental MagT1 transporter and Ca-selective channels (TRPV6), which probably increases the levels of Mg in the placenta and maintains its function in Mg deficiency." (PMID 30717440, 2019).
Infertility (1 paper, 2018). "Disruption of the widely expressed Orai1 store-operated Ca2+-channel interferes with the development of spermatozoa and entails tubular degeneration, whereas the infertility of mice lacking the TRPV6 cation channel was attributed to decreased Ca2+ reabsorption from the epididymal lumen." (PMID 29880644, 2018).
insulinoma (1 paper, 2016). "TRPV6 is present in pancreatic adenocarcinoma and insulinoma cells." (PMID 27450545, 2016).
liver cancer (1 paper, 2019). An epithelial or non-epithelial malignant neoplasm that arises from the liver. "In this study, liver cancer 1MEA cells were also found to overexpress TRPC6 and TRPV6 channels, and immunofluorescence studies showed that Tv1 co-localized with these channels." (PMID 31627357, 2019). "In this study, Tv1, a venom peptide from predatory marine snail T. variegata showed specific and selective cytotoxicity for murine liver cancer cells by binding to the tumor cell membrane and modulating TRPC6 and/or TRPV6 ion channels." (PMID 31627357, 2019).
malaria (1 paper, 2012). Malaria is a serious and sometimes fatal disease caused by a parasite that commonly infects a certain type of mosquito which feeds on humans. "HDIs contain several candidate genes for local adaptation identified in previous studies, such as TRPV6, ASPM, prodynorphin [PDYN;], the duffy blood group locus involved in malaria resistance [DARC;], or the ectodysplasin A receptor [EDAR;]." (PMID 22439654, 2012).
non-small cell lung carcinoma (1 paper, 2017). A group of at least three distinct histological types of lung cancer, including non-small cell squamous cell carcinoma, adenocarcinoma, and large cell carcinoma. "The TRPV6 gene has also been suggested to influence prognosis in cervical- and esophagus squamous cell cancer, as well as in non-small cell lung cancer." (PMID 29299148, 2017).
Osteopenia (1 paper, 2020). Osteopenia is a term to define bone density that is not normal but also not as low as osteoporosis. "Similarly, TRPV6 expression in osteoclast precursors is upregulated by estrogens and TRPV6 knockout mice display osteopenia, indicating that this channel also has an important role in the control of osteoclastogenesis." (PMID 32471309, 2020).
osteosarcoma (1 paper, 2011). A usually aggressive malignant bone-forming mesenchymal neoplasm, predominantly affecting adolescents and young adults. "Our initial aim was to characterize the contribution of TRPV6 ion channels to Ca2+ currents in whole cell patch clamped SaOS-2 osteosarcoma cells." (PMID 22163264, 2011).
pancreatic NETs (1 paper, 2016). "Among pancreatic NET cell lines BON-1 showed a high TRPV6 expression, whereas QGP-1 poorly expressed TRPV6." (PMID 27450545, 2016). "In the present study, we specifically showed that different human pancreatic NET cell lines (BON-1, QGP-1) as well as colonic LCC18 NET cells express TRPV6 at mRNA and protein levels, however at striking differences." (PMID 27450545, 2016).
parathyroid adenomas (1 paper, 2014). "Our findings probably suggest that altered TRPV5 and TRPV6 expression might be associated with parathyroid adenoma." (PMID 25164318, 2014). "Semi-quantitative and quantitative PCR was carried out to evaluate the presence of TRPV5 and TRPV6 mRNAs in sporadic parathyroid adenomas and normal parathyroid glands." (PMID 25164318, 2014). "All in all, our results show the presence of TRPV5 and TRPV6 channels in both normal parathyroid glands and parathyroid adenomas." (PMID 25164318, 2014). "In the present study, for the first time, we provide evidence of the presence of TRPV5 and TRPV6 in human parathyroid glands and their protein overexpression in the parathyroid adenomas." (PMID 25164318, 2014). "Taking into account the regulatory role of the BSPRY and the involvement in cell proliferation of TRPV5/TRPV6, we investigated the presence of both channels in parathyroid adenoma and in parathyroid normal gland, either at mRNA or protein level." (PMID 25164318, 2014). "The comparative quantitative PCR showed that parathyroid adenomas had a lower level of expression with respect to the pool of normal parathyroid glands (P < 0.001), both for TRPV5 and TRPV6 genes, which was on average 16 and fourfold less respectively." (PMID 25164318, 2014).
primary hyperparathyroidism (1 paper, 2023). "In the present study, two cases (ID4 and ID30) were diagnosed with primary hyperparathyroidism in young adulthood and carried a single TRPV6 variant." (PMID 37810884, 2023).
psoriasis (1 paper, 2026). An autoimmune condition characterized by red, well-delineated plaques with silvery scales that are usually on the extensor surfaces and scalp. "Growing evidence suggests the involvement of multiple TRP subtypes in the pathogenesis of psoriasis, including altered expression of vanilloid subtypes, such as TRPV1, TRPV3, TRPV4, TRPV6, the canonical TRPC6, and melastatin TRPM8 in patients." (PMID 41689746, 2026).
steatosis (1 paper, 2021). Increased lipid within the cytoplasm of cells. "MS further increased intestinal villus absorption area and height, increased steatosis, decreased Calb positivity in the intestine and kidney, increased uterine positivity of Calb, and increase Calb and TRPV6 expression in the kidney (P≤0.001) under thermoneutrality." (PMID 33449938, 2021).